YTHDF2 (YTH N6-methyladenosine RNA binding protein F2)
Diseases named in the same sentence as YTHDF2 in open-access papers (continued):
Sharing a sentence is not in itself a finding about the gene and the disease.
cancer (continued). "To provide a more comprehensive evaluation of YTHDF2 expression in cancers, we used the online database Gene Expression Profiling Interactive Analysis (GEPIA) to compare YTHDF2 expression across 33 TCGA cancer types and in TCGA and GTEx normal tissues." (PMID 32986017, 2020). "Compared with the control group, expression levels of HNRNPC, YTHDF1, KIAA1429, RBM15, YTHDF2, and METTL3 in cancer group were significantly up-regulated (P < 0.05), while expression levels of FTO, ZC3H13, METTL14, YTHDC1, and WTAP in cancer group were significantly down-regulated (P < 0.05)." (PMID 33193582, 2020). "In addition, other enrolled in cox formula m6A-related genes METTL14, YTHDF2, ALKBH5 played an oncogenic role in various cancers in a m6A- dependent manner." (PMID 32526707, 2020). "Moreover, YTHDF2 is upregulated in AML and is essential for cancer initiation and metastasis via regulation of m6A-modified transcripts." (PMID 32709063, 2020). "In hepatocellular carcinoma, YTHDF2 suppresses the mitogen-activated protein kinase 1 (ERK)/mitogen-activated protein kinase 7 (MEK) signaling pathway by reducing EGFR expression and subsequently inhibits cancer cell proliferation and growth." (PMID 32709063, 2020). "RNA methyltransferases (such as METTL14, METTL3 and TAP), the demethylases(such as ALKBH5 and FTO), and the binding proteins (such as YTHDF2 and YTHDF1) are often upregulated in a variety of human cancer types to increase the expression of oncogenes and oncoproteins." (PMID 33136551, 2020). "In concert, PT2385 upregulates YTHDF2 expression without changing its cytosolic distribution, which optimizes YTHDF2 function in hypoxic cancer." (PMID 31735169, 2019). "Even though direct involvement of m6A in Wnt pathway has not been reported, YTHDF2, an m6A reader, has been shown to suppress cancer cell migration by inhibiting EMT in an m6A dependent manner." (PMID 30601803, 2019). "In addition to the writers and erasers of m6A modification, the readers, including YTHDF1, YTHDF2, and IGF2BP1, may represent potential biomarkers for responses to cancer immunotherapies." (PMID 39987091, 2025). "The ability for YTHDF2 to form condensate may provide an additional explanation for the control of m6A methylations of OCT4 mRNA by YTHDF2, in turns its effect on promoting the cancer stem cell (CSC) liver phenotype and facilitating cancer metastasis." (PMID 39777266, 2024). "Additionally, YTHDF2 is very important for maintaining the growth of TNBC cells, which reduced the methylated transcripts in high-level transcription and translation processes in the cancer cells where higher MYC expression was observed." (PMID 37469704, 2023). "In addition, YTHDF2 is also positively correlated with TMB and MSI in some cancer types." (PMID 36120577, 2022). "In prostate cancer, METTL3 improves the YTHDF2–HNRNPD-recognized degradation of ubiquitin-specific peptidase 4 (USP4) by mediating m6A modification on A2696 and then maintains the ubiquitin of ELAV-like RNA-binding protein 1 (ELAVL1), giving rise to the migration and invasion of cancer cells." (PMID 35804965, 2022). "Our results revealed that in GBM cancer cells, expression of CD274 (PD-L1), PDCD1LG2 (PD-L2), LGALS9 (Galectin-9), and PVR (CD155) were positively correlated with the expression of multiple m6A regulators, especially YTHDF2, YTHDF3, LRPPRC, METTL3, RBM15B, FTO, and ALKBH5." (PMID 35558067, 2022). "In addition, the overexpression of miR-145 inhibits cancer cell proliferation, while this suppression is impaired by the overexpression of YTHDF2, resulting in a crucial crosstalk between miR-145 and YTHDF2 by forming a double-negative feedback loop." (PMID 35004679, 2021). "GSEA indicated that multiple cancer signaling pathways (mTOR pathway, GSK3 pathway, EIF4 pathway, CHREBP2 pathway, MET pathway, NFAT pathway, FAS pathway, EDG1 pathway, AKT pathway, and CTCF pathway) were differentially enriched in YTHDF2 increased expression phenotype." (PMID 33102202, 2020).
cancer (continued). "In this cancer type, FTO was upregulated in metastases, and demethylation of HOXB13 mRNA led to a decreased decay by lack of YTHDF2 recognition." (PMID 37369946, 2023). "Although YTHDF2, YTHDF3, and YTHDC1 showed essential roles in multiple cancer types, to date, no research on these regulators in COAD has been conducted." (PMID 32596399, 2020). "Therefore, YTHDF2 could display a negative effect in regulating the stability of EGFR and then affect the MAPK/ERK pathway, which inhibits the growth of cancer." (PMID 35382893, 2022).
infection (26 papers, 2011 to 2025). The state of being infected such as from the introduction of a foreign agent such as serum, vaccine, antigenic substance or organism. "aureus, siNC vs. siYTHDF2) identified infection-responsive transcripts and highlighted those potentially regulated by YTHDF2." (PMID 40521032, 2025). "YTHDF2 RIP-seq was used to define its direct mRNA targets, and the integration of these data with m6A profiling identified infection-specific mRNAs that were directly bound by YTHDF2." (PMID 40521032, 2025). "After treatment of OGD/R, very little death and high confluence was seen in cells overexpressed YTHDF2, while large portion of cell death emerged in cells with control infection." (PMID 40273066, 2025). "This analysis enabled the identification of genes altered during infection and those affected by YTHDF2." (PMID 40521032, 2025). "After 26695 infection, ChIP was performed again using YTHDF2 antibody and the PCR results showed higher expression in HP infection group than PBS group." (PMID 39744419, 2025). "This analysis facilitated the identification of genes altered during infection and those affected by YTHDF2." (PMID 40521032, 2025). "In keeping with these findings, the mRNA levels of METTL3 & METTL14 (m6A writers), ALKBH5 & FTO (m6A erasers), and YTHDF2 (m6A reader) were significantly increased in a time-dependent fashion in Huh7 cells post SFTSV infection." (PMID 39585899, 2024). "HeLa cells were transfected with siRNAs targeting METTL3 or YTHDF2 to silence their expression, followed by infection with CVB3." (PMID 39597541, 2024). "They observed that following the knockdown of METTL3 or YTHDF2, infection leads, through effects independent from the viral mechanisms, to the upregulation of many genes involved in the Type I IFN response, ultimately restricting viral proliferation." (PMID 37509095, 2023). "A recent publication demonstrated that the m6A reader gene Ythdf2 is overexpressed in mouse natural killer cells after infection with murine cytomegalovirus (Murid betaherpesvirus 1)." (PMID 37531635, 2023). "Using a single round infection assay, we first showed that subunits of the methyltransferase complex and the cytoplasmic reader YTHDF2 down regulate the levels of HIV RNAs." (PMID 35101069, 2022). "For example, an increase of the YTHDF2 reader protein was observed 1.5 days post infection, which was accompanied by a decrease in YTHDF3." (PMID 36144356, 2022). "We do not have a mechanistic explanation for this unexpected result but hypothesize that the YTHDF2 protein is rescuing infections that are otherwise abortive, possibly by boosting viral gene expression early after infection." (PMID 29447282, 2018). "They showed that overexpression of YTHDF1–3 proteins in HEK293T cells enhanced HIV-1 mRNA and protein expression in a single-cycle infection, and that overexpression or knockout of YTHDF2 in CEM-SS T-cells increased or decreased HIV-1 replication and protein expression, respectively." (PMID 27371828, 2016). "Therefore, the timely application of melatonin during early stages of infection may positively regulate YTHDF2 and negatively regulate METTL3 to inhibit viral replication." (PMID 35897696, 2022). "The mRNA abundance of methyltransferase METTL3, and m6A-specific binding protein YTHDF2 and YTHDF3 significantly increased from 18 h to 24 h after infection." (PMID 40663568, 2025). "Western blot analysis was used to confirm the infection efficiency of Sh‐HIF‐1α and Sh‐EZH2, as well as the knockdown efficiency of Si‐ALKBH5 and Si‐YTHDF2." (PMID 38344897, 2024). "The results showed that the protein level of YTHDF2 gradually decreased as infection progressed, and FMDV-VP1Q209A lost its ability to reduce YTHDF2 expression." (PMID 38516932, 2024). "In all cases, the infection of METTL3- and YTHDF2-depleted cells led to enhanced IFNB and ISG15 expression." (PMID 37509095, 2023).
infection (continued). "The result suggested that the infection of LV‐YTHDF2 in T98G and LN229 cells reduced the luciferase activity of TNFAIP3‐WT (with m6A sites), and the infection of LV‐Sh‐YTHDF2 in T98G/TR and LN229/TR cells increased the luciferase activity of TNFAIP3‐WT." (PMID 35582627, 2022). "Immunofluorescence (IF) signals of both YTHDF1 and YTHDF2 in GC axons were also significantly reduced after infection of shYthdf1 or shYthdf2, suggesting that axonal YTHDF1 and YTHDF2 signals are specific." (PMID 34643063, 2021). "Over the course of infection, levels of the assayed writers (METTL3, METTL14, and WTAP) and readers (YTHDC1, YTHDF1, and YTHDF2) remain unchanged." (PMID 33243990, 2020). "Upon infection with CVB3, the results revealed that the knockdown of YTHDF1 and YTHDF2 resulted in significant reductions in CVB3 RNA copies, VP1 proteins, viral titres and GFP expression, whereas the knockdown of YTHDF3 led to a decrease in only CVB3 RNA copies and GFP expression." (PMID 39339923, 2024). "Notably, the knockdown of YTHDF2 and METTL3 proteins resulted in a decrease in viral replication at 24 hours post infection (hpi), which were consistent with a previous study." (PMID 37053288, 2023). "Furthermore, the infection of LV‐YTHDF2 in T98G and LN229 cells reduced the luciferase activity of EPHB3‐WT (with m6A sites), and the infection of LV‐sh‐YTHDF2 in T98G/TR cells and LN229/TR cells increased the luciferase activity of EPHB3‐WT." (PMID 35582627, 2022). "However, similar to the infection with CMV, the reader protein YTHDF2 has also been involved with an antiviral activity; in this case specifically mediating viral transcript degradation." (PMID 36144356, 2022). "The results showed that the protein levels of METTL3, METTL14, and YTHDF2 did not change significantly in A549 cells during infection by influenza virus WSN/1933." (PMID 35583334, 2022). "Furthermore, we found that the m6A readers, YTHDF2 and IGF2BP3, interacted considerably with the three lncRNAs in all infection states and promoted lncRNA stability." (PMID 36369338, 2022). "However, both the LV‐YTHDF2 and LV‐sh‐YTHDF2 infections exerted no significant influence on the luciferase activity of EPHB3‐Mut (with mutant m6A sites)." (PMID 35582627, 2022). "Stable IKKγ and p65 transcripts underwent YTHDF2-dependent mRNA decay, whereas DHX58 translation was promoted, resulting in inhibited antiviral innate response by DDX5 via blocking the p65 pathway and activating the DHX58-TBK1 pathway after infection with RNA virus." (PMID 33909701, 2021). "Using VExD, we find that the human ortholog YTHDF2 is also overexpressed in response to human cytomegalovirus (CMV, Human betaherpesvirus 5) infections, but not to other virus types." (PMID 37531635, 2023). "Thus, our results indicate that YTHDF2, but not YTHDF1 and YTHDF3, decreases HIV-1 RNA abundance in a single round infection assay." (PMID 35101069, 2022). "Similarly, depletion of the YTHDF2, but not YTHDF1 or YTHDF3, increased the levels of HIV-1 transcripts in a single round infection assay." (PMID 35101069, 2022).
bacterial infection (5 papers, 2022 to 2025). "Another report showed that YTHDF2 negatively modulated the inflammatory response caused by bacterial infection." (PMID 38026444, 2023). "Furthermore, YTHDF2 plays a critical role in modulating apoptosis, mitochondrial function and ROS levels, thereby supporting cell survival during bacterial infection." (PMID 40521032, 2025). "Importantly, YTHDF2 was significantly induced during bacterial infections, which maximized its negative regulation of DUSP1 transcript stability." (PMID 36625590, 2023). "However, it is possible that HSV-1 infection might have a YTHDF2 induction kinetic that is different from those of bacterial infections." (PMID 36625590, 2023). "Here, we report that in response to viral and bacterial infections, not only the DUSP1 transcript but also its N6-methyladenosine (m6A) levels rapidly increase together with that of the m6A reader protein YTHDF2, resulting in enhanced YTHDF2-mediated DUSP1 transcript degradation." (PMID 36625590, 2023).
colon (3 papers, 2021 to 2024). "M6A reader YTHDF2-mediated degradation of ADAMTS9-AS2 promotes colon carcinogenesis via miR-27a-3p/BTG2 axis." (PMID 36816363, 2023). "For the downstream of YTHDF2, we used GEO databases to identify the STAT5A in gastrointestinal tumors." (PMID 37256443, 2024).
cardiovascular disease (2 papers, 2022). "By searching for the potential targets of miR-877-3p, we found that among the potential targets regulated by miR-877-3p, GADD45g, NSUN2, YTHDF2 and MTUS1 have regulatory roles in the involvement of cardiovascular disease 30-32." (PMID 35928721, 2022).
metabolic disorders (2 papers, 2020 to 2025). "However, the role of YTHDF2 in ccRCC metabolic disorders remains unknown." (PMID 33102202, 2020).
adenocarcinoma (1 paper, 2022). A common cancer characterized by the presence of malignant glandular cells. "Representative figures of immunohistochemistry in adenocarcinoma show that high YTHDF1 or YTHDF2 cases are associated with low CD4, CD8 and high FOXP3 expression in both PD-1 inhibitor treatment and non-treatment groups." (PMID 36479088, 2022). "However, four immune-associated gene sets related to YTHDF2 were found in adenocarcinoma." (PMID 36479088, 2022). "The YTHDF1 or YTHDF2 mRNA expression was significantly negatively associated with CD4, CD8, and FOXP3 mRNA expression in adenocarcinoma." (PMID 36479088, 2022). "In adenocarcinoma, YTHDF2 was negatively correlated with CD4 and CD8 and positively correlated with FOXP3 in protein and mRNA analysis." (PMID 36479088, 2022). "YTHDF1 has an immune hot profile in both cell types, whereas YTHDF2 is only seen in adenocarcinoma." (PMID 36479088, 2022). "In the adenocarcinoma group not receiving PD-1/PD-L1 inhibitor, the cutoff values of YTHDF1 and YTHDF2 were 60 and 75, respectively." (PMID 36479088, 2022).
infectious disease (1 paper, 2022). A disorder directly resulting from the presence and activity of a microbial, viral, or parasitic agent in humans. "In the study of infectious diseases, YTHDF2 upregulation promotes HIV-1 and HBV levels as well as viral replication ability." (PMID 36277978, 2022).
neurological disorders (1 paper, 2026). "Ythdf2 encodes the N6-methyladenosine (m6A) reader protein YTHDF2, which is an RBP that recognizes and directs m6A-modified RNAs; its dysregulation has been implicated in a number of neurological disorders." (PMID 41397872, 2026).
YTHDF2 also shares sentences with these, for which no sentence is quoted: uterine corpus endometrial carcinoma (5 papers); Parkinson disease (4); bladder urothelial carcinoma (3); breast invasive carcinoma (3); cervical squamous cell carcinoma (3); cutaneous melanoma (3); esophageal cancer (3); ischemic stroke (3); periodontitis (3); prostate adenocarcinoma (3); rectum adenocarcinoma (3); renal carcinoma (3); sarcoma (3); stomach adenocarcinoma (3); uveal melanoma (3); amyotrophic lateral sclerosis (2); Hyperglycemia (2); hypertrophy (2); idiopathic pulmonary fibrosis (2); neurodegenerative disease (2); preeclampsia (2); acute leukemia (1); adrenocortical carcinoma (1); alopecia (1); Alzheimer disease (1); anaplastic oligoastrocytoma (1); ankylosing spondylitis (1); Anxiety (1); asthenozoospermia (1); autism (1).
A further 46 diseases each share a sentence with YTHDF2 in 1 paper.